RNU7-169P (RNA, U7 small nuclear 169 pseudogene)
Gene: Small nuclear RNA gene on chromosome 12 (108,668,448 to 108,668,508, forward strand). Ensembl gene ENSG00000238457.
Homologues: Orthologues: chimpanzee U7 (98% identical), macaque U7 (95% identical). Paralogues in human: RNU7-35P (80% identical), RNU7-125P (79% identical), RNU7-28P (79% identical), RNU7-97P (79% identical), RNU7-128P (77% identical), RNU7-18P (77% identical), RNU7-20P (77% identical), RNU7-25P (77% identical), RNU7-41P (77% identical), RNU7-45P (77% identical), RNU7-48P (77% identical), RNU7-73P (77% identical), and 142 more.